ALB (albumin)
Diseases named in the same sentence as ALB in open-access papers (continued):
Sharing a sentence is not in itself a finding about the gene and the disease.
status epilepticus (13 papers, 2006 to 2026). Status epilepticus is defined as a continuous seizure lasting more than 30 min, or two or more seizures without full recovery of consciousness between any of them. "Two further deaths in the Gelofusine group (cases 7 and 9) in addition to the sole albumin fatality (case 11) were associated with refractory status epilepticus, where optimal seizure control was compromised by respiratory depression." (PMID 16998584, 2006). "Albumin concentration reportedly increases in the cerebrospinal fluid due to dysfunction of the blood–brain barrier following seizures or status epilepticus; moreover, albumin is released from the blood into the brain tissue due to seizures." (PMID 39723425, 2024). "For example, a model of status epilepticus in rats resulted in extravasation of albumin in the hippocampus, which was diffusely distributed at 2 h post status epilepticus and became concentrated in CA3 neurons at 24 h." (PMID 27067000, 2016). "Status epilepticus (SE), complications, endotracheal intubation, mRS score at discharge, APE2, and RITE2 scores increased the risk of poor prognosis (OR > 1), while intensive care and albumin reduced the risk (OR < 1)." (PMID 39539648, 2024). "To test this hypothesis, here we assessed in a mouse model of TLE whether aberrant albumin-mediated TGFβR1/ALK5 signaling upon kainate-induced status epilepticus (SE) induces astrocyte uncoupling and epileptogenesis." (PMID 34025561, 2021). "However, with status epilepticus, there is a known loss of integrity at the BBB with the entry of proteins such as albumin." (PMID 33177978, 2020). "Acute-phase proteins, such as procalcitonin (PCT), C-reactive protein (CRP) and albumin, may relate with course and outcome in status epilepticus (SE), as seizures bring about inflammation, changes of cytokine levels and blood–brain barrier breakdown." (PMID 26450065, 2015). "Our study aimed to investigate whether the monocyte‐to‐albumin ratio (MAR), a novel marker of systemic inflammation, could serve as a predictor of functional outcomes in status epilepticus (SE)." (PMID 41540788, 2026). "These include the presence of acute brain lesions, increased severity of status epilepticus (measured using the status epilepticus severity score [STESS]), non-convulsive status epilepticus with coma, and increased serum albumin levels at onset of status epilepticus." (PMID 37114231, 2023). "However, hippocampal tissue from chronic epileptic humans and status epilepticus mouse model exhibited a well-maintained BBB permeability to two differently sized tracers, TMR and Alexa488 labelled-bovine serum albumin, compared to WT samples when assessed with ISMICAP." (PMID 37993886, 2023).
arteriosclerosis (12 papers, 2014 to 2024). A vascular disorder characterized by thickening and hardening of the walls of the arteries. "Decreased PCX expression was also associated with higher urinary protein levels, lower plasma ALB, decreased eGFR, and more severe tubule interstitial inflammation and arteriosclerosis (P < 0.01)." (PMID 32337271, 2020). "Compression of small arteries leads to arteriosclerosis of the renal arteries, thickening of the vascular wall, narrowing of the lumen, and increased glomerular filtration pressure and filtration rate, further causing increased albumin filtration." (PMID 39022345, 2024). "Biomarkers of vascular-related diseases such as homocysteine (Hcy), N-terminal pro-brain natriuretic peptide (NT-proBNP), and urine albumin (microalbumin) (UAE) have involved the pathophysiological development of arteriosclerosis." (PMID 32537254, 2020). "Recent studies showed that plasma biomarkers such as homocysteine (Hcy), N-terminal pro-brain natriuretic peptide (NT-proBNP), and urine albumin (microalbumin) (UAE) have involved the pathophysiological development of arteriosclerosis and could be predictors of future cardiovascular events." (PMID 32537254, 2020). "In the second multivariable model, clinical features (baseline eGFR, urine proteinuria and albumin) and RPS glomerular class, IFTA or modified arteriosclerosis score were included." (PMID 34407751, 2021). "In our study, glomerular lesions and IFTA were statistically significant in both univariate and pathological models but not after adjustment for proteinuria, eGFR, serum albumin levels, or arteriosclerosis." (PMID 34407751, 2021).
autoimmune hepatitis (12 papers, 2006 to 2026). Hepatitis caused by autoantibodies. "The sensitivity and specificity of the hemoglobin, albumin, lymphocyte, and platelet score were higher than the Fibrosis-4 score in predicting moderate/advanced fibrosis in autoimmune hepatitis." (PMID 38294124, 2024). "The hemoglobin, albumin, lymphocyte, and platelet score was significantly reduced in autoimmune hepatitis patients than healthy controls (p<0.001)." (PMID 38294124, 2024). "A hemoglobin, albumin, lymphocyte, and platelet score that was lower than 52.3 had 83% sensitivity and 73% specificity in predicting autoimmune hepatitis." (PMID 38294124, 2024). "The aim was to examine the hemoglobin, albumin, lymphocyte, and platelet score of patients with autoimmune hepatitis and to compare it to that of healthy individuals in this retrospective analysis." (PMID 38294124, 2024). "The mean hemoglobin, albumin, lymphocyte, and platelet score of the autoimmune hepatitis patients was 44.2±14.5 while this value was 76.8±15.5 in control subjects." (PMID 38294124, 2024). "Furthermore, aspartate to platelet ratio index, Fibrosis-4, and hemoglobin, albumin, lymphocyte, and platelet scores of the autoimmune hepatitis patients and controls were compared." (PMID 38294124, 2024). "In addition, the hemoglobin, albumin, lymphocyte, and platelet score of the autoimmune hepatitis patients with mild fibrosis is compared to that of those with moderate/advanced fibrosis." (PMID 38294124, 2024). "Collectively, these findings suggest that simple and widely available clinical parameters—such as serum albumin, ESR, ANA titers, and disease duration—may serve as practical tools to stratify the risk of polyautoimmunity in patients with autoimmune liver diseases." (PMID 40725836, 2025). "At 20 weeks of age, sera from WT and mutants had similar levels of liver enzymes (ALT, AST, ALP) and albumin, suggesting that mutants did not have autoimmune hepatitis." (PMID 37275873, 2023).
capillary leak syndrome (12 papers, 2013 to 2025). A syndrome characterized by leakage of intravascular fluids into the extravascular space. "Second, in patients with increased capillary permeability or capillary leak syndrome, albumin administration may exacerbate or cause pulmonary edema as a result of albumin and water crossing the capillary membrane, which may compromise tissue oxygenation and result in multiorgan failure." (PMID 40649163, 2025). "Additionally, critical illness-associated inflammation and capillary leak syndrome, which are typically more pronounced in shock states requiring vasopressors, may substantially reduce ALB levels." (PMID 41268109, 2025). "A decrease in albumin in initial cancer treatment days has suggested a predictor of capillary leak syndrome when treated with gemcitabine." (PMID 37261188, 2023). "Critically ill patients had increased oxygen consumption, when these patients accompanied with capillary leak syndrome, they often had hydration status resulting in increasing reabsorption of urea by the kidneys, and reduction of ALB, elevation of BUN level can be frequently observed." (PMID 32787942, 2020). "A predictor, although a little sensitive, of capillary leak syndrome is the decrease of albumin." (PMID 24215543, 2013).
chronic lung disease (12 papers, 2018 to 2025). According to the definitions of the American and British Thoracic Societies, including pulmonary functional tests, X-rays, and CT scans for items such as fibrosis, bronchiectasis, bullae, emphysema, nodular or lymphomatous abnormalities. "The first important finding of this study was that elderly age (>60 years), female gender, lower body height and weight, higher body adiposity index and body roundness index, lower hematocrit, higher glycohemoglobin, and lower albumin level had the higher risk for chronic lung diseases." (PMID 34442463, 2021). "Other risk factors for pulmonary infections were female sex, concurrent chronic lung disease, older age, longer surgery duration, longer extubation time, higher neutrophil count, and lower albumin level." (PMID 40017523, 2025). "This algorithm, derived from univariable and multivariable logistic regression analyses, incorporates preoperative and operative factors, including age, sex, chronic lung disease, dialysis, preoperative serum Hb, serum albumin, CPB time, NYHA classification, and left ventricular ejection fraction." (PMID 40429397, 2025).
deficiencies (12 papers, 2013 to 2025). "Several factors cause weight loss such as pre-treatment nutritional deficiencies, acute mucositis, tobacco smoking, radiation doses to organs at risk (such as parotids), serum albumin levels, BMI." (PMID 33924581, 2021). "The albumin deficiency rate was highest in the BMI ≥ 47.5 kg/m2 group, and the 25 (OH) D deficiency rate was highest in the 37.5–42.5 kg/m2 BMI group." (PMID 34322512, 2021). "Patients with different BMIs had different albumin deficiency (χ2 = 11.634, P = 0.015) and 25 (OH) D (χ2 = 9.532, P = 0.049) deficiency rates." (PMID 34322512, 2021). "Decreased plasma albumin has been considered as a risk factor for nutritional deficiencies and frailty in the elderly." (PMID 34835952, 2021). "In addition, 25 (OH) D deficiency and albumin deficiency were more common in patients with BMI ≥ 47.5 kg/m2 (P = 0.049 and 0.015, respectively)." (PMID 34322512, 2021). "With respect to overweight patients, the survey results also revealed vitamin D and protein deficiencies in all groups; in particular, patients in the SG exhibited significantly lower protein levels (i.e., albumin level and total protein in serum) than those in both CGs." (PMID 32424439, 2021).
head and neck squamous cell carcinoma (12 papers, 2021 to 2026). A squamous cell carcinoma that arises from any of the following anatomic sites: lip and oral cavity, nasal cavity, paranasal sinuses, pharynx, larynx, and salivary glands. "Furthermore, in head and neck squamous cell carcinoma, higher serum Albumin (ALB) levels are correlated with a lower risk of irAEs, which may be related to the role of nutritional status in regulating the immune system." (PMID 40182043, 2025). "We investigated the prognostic significance of the preoperative albumin-bilirubin (ALBI) score in surgically treated head and neck squamous cell carcinoma (HNSCC)." (PMID 40999594, 2025). "Serum albumin measured on the first postoperative day was the only variable that was a predicter of postoperative complications after major head and neck squamous cell carcinoma surgery." (PMID 33875388, 2022). "In particular, low pretreatment serum albumin was linked to worse disease-free survival (DFS), cancer-specific survival and OS in head and neck squamous cell carcinomas." (PMID 35052870, 2022). "Additionally, a study demonstrated that pretreatment albumin levels predicted survival outcomes in head and neck squamous cell carcinoma." (PMID 38500655, 2024). "One study examined the clinical utility of pretreatment serum ALB in patients with head and neck squamous cell carcinoma (HNSCC)." (PMID 34539891, 2021). "Preclinical and clinical studies have investigated the use of EphB4-Human Serum Albumin Fusion Protein (sEphB4-HAS) in the treatment of cancer, particularly head and neck squamous cell carcinoma (HNSCC)." (PMID 40421081, 2025).
Hydrocephalus (12 papers, 2011 to 2026). Hydrocephalus is an active distension of the ventricular system of the brain resulting from inadequate passage of CSF from its point of production within the cerebral ventricles to its point of absorption into the systemic circulation. "For instance, Gao and colleagues used an IVH model in rats, where blood was directly injected into the lateral ventricles, showing that simultaneous thrombin injections resulted in hydrocephalus and increased levels of albumin in peri-ventricular areas indicative of loss of BBB function." (PMID 34359845, 2021). "When radiolabeled serum albumin was administered intravenously to infants with communicating hydrocephalus, 4–9 h later radioactivity was highest in lumbar fluid, intermediate in cisternal and lowest in ventricular fluid." (PMID 35794632, 2022). "In normal pressure hydrocephalus, leukocyte count in lumbar CSF is normal (≤ 4/μl), and CSF-to-serum albumin ratio and CSF protein content are normal or slightly elevated." (PMID 35794632, 2022). "Increased risk of hydrocephalus in untreated SMA patients and a marginal but significant increase of the serum/CSF albumin ratio (Qalb) with rare cases of communicating hydrocephalus during treatment with the ASO nusinersen were reported." (PMID 34321067, 2021). "Increased risk of hydrocephalus in untreated SMA patients and a marginal but significant increase of the serum/CSF albumin ratio (Qalb) with rare cases of communicating hydrocephalus during nusinersen treatment were reported, which confirms the unmet need of an inflammatory biomarker in SMA." (PMID 34321067, 2021). "Cytotoxic lymphocytes and macrophages produce proteases, that in theory could act on albumin, but albumin fragmentation has been observed in the CSF from hydrocephalus, which results in a different inflammatory profile than MS." (PMID 27067000, 2016). "For the univariate analysis, the results revealed that preoperative hydrocephalus (p = 0.01), SII (p = 0.006), albumin–bilirubin score (ALBI) (p = 0.04), and coSII–PNI were predictors of OS." (PMID 34977115, 2021). "Aquaporin 4 null mice, which develop hydrocephalus, have intact BBB as judged by intravenous injection of Evans blue dye (which forms a complex with plasma albumin, MW 69 kDa)." (PMID 21834998, 2011). "Perfusion of 125I-albumin (MW 69 kDa) or type II horseradish peroxidase (HRP; MW ~44 kDa) into the ventricles of cats with kaolin-induced hydrocephalus revealed no reverse flow across the BBB." (PMID 21834998, 2011).
metastatic colorectal cancer (12 papers, 2015 to 2026). "In recent years, several observational studies have investigated the association between C-reactive protein to albumin ratio (CAR) and prognosis of metastatic colorectal cancer (mCRC), and yielded controversial outcomes." (PMID 34797305, 2021). "Meta-analysis of the correlation between C-reactive protein to albumin ratio and clinicopathological characteristics of metastatic colorectal cancer." (PMID 34797305, 2021). "The CRP/ALB ratio is a useful marker not only for predicting survival, but also for monitoring chemotherapeutic effectiveness in patients with unresectable metastatic colorectal cancer who receive palliative chemotherapy." (PMID 27812440, 2016). "The CRP/ALB ratio is a useful marker for predicting survival and monitoring chemotherapeutic effectiveness in patients with unresectable metastatic colorectal cancer." (PMID 27812440, 2016). "Wei Wei Y Y Prognostic significance of serum lactic acid, lactate dehydrogenase, and albumin levels in patients with metastatic colorectal cancer Prognostic significance of serum lactic acid, lactate dehydrogenase, and albumin levels in patients with metastatic colorectal cancer Biomed." (PMID 40664764, 2025). "Taken together, the levels of ALB, LDH, SLA, and CA199 measured before first chemotherapy in patients with metastatic colorectal cancer may serve as a marker of deterioration and chemoresistance." (PMID 30627541, 2018). "We compared the level of serum ALB, SLA, and LDH measured before the first-line chemotherapy in patients with metastatic colorectal cancer and before adjuvant chemotherapy in patients with nonmetastatic cancer." (PMID 30627541, 2018).
nephrosis (12 papers, 2012 to 2025). Pathological processes of the KIDNEY without inflammatory or neoplastic components. "They develop nephrosis associated with hypoalbuminemia and elevated urine albumin/creatinine ratio (ACR)." (PMID 33755599, 2021). "The decrease in the J substrain was milder, although a similar trend of decrease in serum albumin was observed with ADR-nephrosis at week 6 compared to baseline/week 0 (4.04 ± 0.4 g/dl vs. 4.26 ± 0.2 g/dl)." (PMID 35784478, 2022). "Intragroup analysis in the II and ID/DD at the time of diagnosis and at study recruitment revealed that parameters related to nephrosis (serum albumin, uPCI and lipid profiles) had improved significantly in both groups at follow-up." (PMID 24883149, 2014). "In this work we did not observe a change in ENaC subunit expression; however, this may reflect differences in the models studied (puromycin induced nephrosis vs. albumin overload)." (PMID 27323402, 2016). "Conversely, chronically increased albumin stimulation in nephrosis may disturb this homeostatic balance, thus favouring the development of the typical renal histological changes of progressive tubulointerstitial disease." (PMID 23346243, 2012). "However, the patients in the II group were younger (27 vs. 33 years old), had lower serum creatinine (87 vs. 93.5 μmol/L) and higher eGFR (88 vs. 63 mL/min/1.73 m2) despite having more severe nephrosis with uPCI of 0.56 g/mmol vs. 0.42 g/mmol and serum albumin of 24.4 g/L vs. 25.2 g/L." (PMID 24883149, 2014). "Rupture of the blood-brain barrier exposes cells of the nervous system to unusually high concentrations of albumin, and is thus analogous to the situation faced by PTC in nephrosis." (PMID 23346243, 2012). "Similarly, Sgpl1-KO mice develop nephrosis with high urine albumin/creatinine ratio (ACR) and low serum albumin levels, accompanied by pathological changes consistent with podocyte and glomerular injury prior to their demise at the time of weaning (at 21 DOL)." (PMID 33755599, 2021).